KLK6 (kallikrein related peptidase 6)
Diseases named in the same sentence as KLK6 in open-access papers (continued):
Sharing a sentence is not in itself a finding about the gene and the disease.
colon carcinoma (continued). "The amount of KLK6 found in the ascitic fluids from patients with peritoneal metastasis of colon cancers (0.2 to 40 ng/mL) were in the same range as the KLK6 amount found in ovarian ascites (42 ng/mL)." (PMID 35883559, 2022). "KLK6 expression is upregulated during colon cancer progression; high expression is observed in inflammatory cells in colorectal adenocarcinoma." (PMID 36552865, 2022). "High levels of KLK6 (reaching ~40 μg/L) were present in ascitic fluids of several patients with peritoneal metastasis from colon cancers." (PMID 35883559, 2022). "The analysis of the secreted KLK6 levels was done in three cases, representing the colon cancer samples (P#3 and P#5) and a colon adenoma (P#7)." (PMID 34065672, 2021). "Our analysis suggests that identifying colon cancer patients with KLK6 overexpression and targeting it using specific inhibitors can be beneficial for the suppression of metastasis." (PMID 34065672, 2021). "As we previously reported, KLK6 expression in colon cancer can be induced by the major colon cancer driver gene, oncogenic K-RAS, while the knockdown of KLK6 in colon cancer cells leads to suppression of their invasive and metastatic properties." (PMID 34065672, 2021). "We have previously reported the mutant K-RAS-dependent expression of KLK6 gene in the colon cancer cells, so the current results from TCGA patient data confirmed the validity of the previous findings." (PMID 34065672, 2021). "Recent studies have found that the role of let-7i-5p is to suppress cellular migration and proliferation via HMGA1 gene targeting in bladder cancer and kallikrein-related peptidase 6 in colon cancer." (PMID 32411089, 2020). "We previously established a unique contribution of KLK6 in colon cancer metastasis via a specific network of microRNAs and mRNAs." (PMID 31692974, 2019). "In HCT116 colon cancer cells with KLK6 knockdown (shKLK6 cells) TGF-β2 was identified as one of the top downregulated genes." (PMID 31692974, 2019). "We found that proteolytically active KLK6 increased Caco-2 cells invasiveness in vitro and decreased the animal survival in the orthotopic colon cancer model." (PMID 31692974, 2019). "We further tested the consequences of expressing enzymatically active and inactive KLK6 in Caco-2 isogenic clones in vivo in an SCID orthotopic colon cancer model (N = 10 mice per group)." (PMID 31692974, 2019). "In the present study we investigated the consequences of KLK6 overexpression and its enzymatic activity in colon cancer cells." (PMID 31692974, 2019). "To elucidate the relevance of our in vitro findings of KLK6 function in colon tumorigenesis we assessed the status of the KLK6 protein by IHC in FFPE tissue sections of colon cancer patients (N = 10, described in detail in “Material and Methods” section)." (PMID 31692974, 2019). "A limited analysis of the expression and secretion patterns of KLK6 in CRC patients, point to the individual variations in KLK6 expression and suggest that further stratification of patients is needed when evaluating KLK6 in colon cancer." (PMID 31692974, 2019). "In colon cancer, correlation was established between elevated KLK6 expression and secretion and aggressive tumor behavior and poor patient outcome." (PMID 31692974, 2019). "Future evaluation of β-catenin/E-cadherin complex and/or its translocation to the nucleus will help us to determine the exact function of β-catenin in KLK6 overexpressing colon cancer cells." (PMID 31692974, 2019). "Colon cancer had four up-regulated KLKs with excellent AUC values (KLK6: 0.988, KLK7: 0.939, KLK8: 0.928, KLK10: 0.905)." (PMID 29707153, 2018). "To date, it has been shown that KLK6 is upregulated in such gastrointestinal malignancies as pancreatic and colon cancers." (PMID 23587030, 2013). "Recently, KLK6 expression and secretion has been shown to be Ras dependent in a colon carcinoma cell line." (PMID 19707197, 2009).
colon carcinoma (continued). "Knockdown of KLK6 in colon cancer cells inhibits migration and invasion in vitro." (PMID 40156045, 2025). "We have previously shown the role of KLK6 in colon cancer cell invasion." (PMID 39594797, 2024). "KLK6 and KLK7 have been reported as markers of gastric, breast, and colon cancers and may be associated with m7G modifications." (PMID 37575065, 2023). "Estimation of KLK6 expression in colon carcinoma epithelial cells." (PMID 35883559, 2022). "KLK6 upregulation in colon cancer may be rather influenced by other factors from the tumor microenvironment." (PMID 35883559, 2022). "Whether KLK6 alter adhesion of colon cancer cells via its interaction with integrins or other adhesion molecules will need to be investigated in detail." (PMID 35883559, 2022). "In addition, many studies have shown that aberrant expression of KLK6 in human malignancies, including colon cancer, is often regulated by microRNAs interactions." (PMID 35883559, 2022). "To conclude, we have demonstrated for the first time the consequences of aberrant KLK6 expression in colon cancer derived cell lines and its link to PAR2 receptor signaling, leading to significant ERK1/2 phosphorylation and cell proliferation, presumably by activating PAR2." (PMID 35883559, 2022). "Thus, KLK6 becomes a potential endogenous PAR2 activator in colon cancer owing to its aberrant expression." (PMID 35883559, 2022). "Since KLK6 upregulation is associated with the more aggressive tumor phenotype (this study) and poor prognosis, we investigated if KLK6 could be detected in ascitic fluids from peritoneal metastasis of colon cancers." (PMID 35883559, 2022). "In human colon cancers, KLK6 mRNA has been extensively studied as a clinical biomarker." (PMID 35883559, 2022). "Thus, KLK6 is a colon cancer-produced protease that plays a role in the colon cancer aggressive phenotype and in the metastatic process." (PMID 35883559, 2022). "Moreover, KLK6 suppression in the human colon cancer-derived cell line, HCT116 decreased colony formation and increased cell adhesion to extracellular matrix binding proteins." (PMID 35883559, 2022). "In human colon cancer-derived cell lines, KLK6 levels in the supernatant of colon cancer cells were high (up to 70 μg/L), which is in agreement with the levels found in the sera from patients with colon cancer (10–40 μg/L)." (PMID 35883559, 2022). "Serum KLK6 levels increased in patients with metastatic breast cancer and colon cancer." (PMID 36552865, 2022). "Thus, KLK6 seems to promote an aggressive phenotype of colon cancer cells and deserves further evaluation as a differential marker for benign and malignant ascites." (PMID 35883559, 2022). "Despite the evidence that support the critical role of KLK6 in malignant progression of colon cancer the exact involvement of KLK6 in the different steps of metastasis remains unknown." (PMID 35883559, 2022). "Therefore, we analyzed the presence of KLK6 in ascitic fluids from CRC patients with peritoneal metastasis from colon cancers." (PMID 35883559, 2022). "Still, localized active KLK6 expression in the ascites of colon cancer patients may play a role in spheroid formation to maintain growth and chemoresistance." (PMID 35883559, 2022). "Taken together, these data reveal that many colon cancer-derived cell lines express and secrete immunoreactive KLK6 that may potentially act in the extracellular environment in an autocrine manner and play a role in colon cancer progression." (PMID 35883559, 2022). "It has been reported that the KLK6 gene could be cloned independently of other genes, such as zyme in brain tissue, protease M in breast tissue, and neurosin in a colon carcinoma cell line." (PMID 34858488, 2021). "KLK6 is regulated by mutant K‐RAS in colon cancer cells to enhance their migration and invasion." (PMID 30980596, 2019). "Hence, KLK6 may be further considered as an attractive therapeutic target for the management of aggressive colon cancers." (PMID 35883559, 2022).
colon carcinoma (continued). "Thus, KLK6 seems to promote an aggressive phenotype in colon cancer and may be involved in peritoneal metastasis." (PMID 35883559, 2022). "Moreover, let-7i-5p had been found to inhibit the proliferation and metastasis of colon cancer cells by targeting kallikrein-related peptidase 6 and significantly inhibit gastric cancer proliferation, invasion, and metastasis by targeting collagen type I alpha 1 chain." (PMID 33775245, 2021). "Our data are in contrast to recent findings in other tumor cells lines derived from skin and colon cancer in which KLK6 promotes tumor cell migration and invasion by either E-cadherin ectodomain shedding, activation of protease-activated receptors or so far unknown molecular mechanisms." (PMID 25990935, 2015). "Moreover, KLK6 has been differentially expressed in breast, uterine, and colon cancers." (PMID 25505737, 2014). "RNA-Sequencing data analysis of kallikrein genes across 15 different cancers from the TCGA database highlighted KLK6, KLK7, KLK8, and KLK10 as the candidate genes for further evaluation as colon cancer biomarkers." (PMID 39594797, 2024). "Several members of kallikrein family are overexpressed in colon cancer patients, i.e., KLK4, KLK6, KLK7, KLK10, and KLK14." (PMID 34065672, 2021). "We first assessed the mRNA expression of KLK6, and the other members of the PDAC-specific KLK cluster, in widely used human PDAC cell lines and colon cancer cells as KLK-expressing controls." (PMID 34439122, 2021). "Overall, this pilot analysis confirms the variability of KLK6 expression in the CRC and demonstrates the experimental platform for more detailed analysis of key genes in the colon cancer." (PMID 34065672, 2021). "To understand how KLK6 contributes to the poor prognosis in the CRC patients we stably expressed enzymatically active and inactive KLK6 in Caco-2 colon cancer cells." (PMID 31692974, 2019). "We found that KLK6 is highly expressed in the malignant ascites of patients with peritoneal metastasis of colon cancer in contrast to it being undetectable in non-malignant ascitic fluids from patients with benign liver diseases." (PMID 35883559, 2022). "Three kallikreins, KLK6, KLK7, and KLK8, were found to be overexpressed in colon cancer." (PMID 36293321, 2022). "Our findings are also in agreement with the in silico analysis showing that KLK6 is absent in normal colonic tissues and aberrantly expressed in colonic tumors." (PMID 35883559, 2022). "mRNA analysis of CEACAM5, KLK6, and SLC35D3 improves the detection of tumor cells in lymph nodes from patients surgically treated for colon cancer, and, together with POSTN and MUC2, it further allows characterization of the tumor cells with respect to aggressiveness and the tumor cell environment." (PMID 34192710, 2021). "Using the Caco-KLK6 model and the previously characterized HCT116-shKLK6 cell model we showed that the proteolytic activity of the KLK6 enzyme is directly responsible for the invasive properties of colon cancer cells." (PMID 31692974, 2019). "We found that KLK6 overexpression in colon cancer cells, regardless of its enzymatic activity, induces the expression of transcription associated protein HMGA2, which has been identified as a driver of the CRC progression and metastasis." (PMID 31692974, 2019). "Therefore, we hypothesized that KLK6 may enhance aggregation of colon cancer cells in non-adherent conditions." (PMID 35883559, 2022). "Many in vitro studies have shown that KLK6 may undergo autoactivation or become activated by other proteases including other KLKs, such as KLK14 and KLK5, for which overexpression in human colon tumors has been demonstrated in our previous report and in ongoing work (unpublished data)." (PMID 35883559, 2022). "Therefore, we investigated whether KLK6 can signal through PAR1 and/or PAR2 in colon cancer cells." (PMID 35883559, 2022).
colon carcinoma (continued). "We show by immunohistochemistry that KLK6 is expressed (84%) in resected colonic tumors from the CRC patients and the mucosa from control normal colonic tissues did not stain at all with the KLK6 antibody." (PMID 35883559, 2022). "We employed HCT116 isogenic colon cancer cell model with the negative control cells (HCT116-control shRNA) and cells with knockdown expression of KLK6 (HCT116-KLK6 shRNA cells) and followed cells in culture for 2 weeks." (PMID 35883559, 2022).
gastric cancer (15 papers, 2008 to 2023). A primary or metastatic malignant neoplasm involving the stomach. "For example, KLK6 mRNA overexpression is associated with lymph node invasion and advanced clinical stage of gastric cancer patients, thus predicting poor prognosis for these patients." (PMID 29229980, 2017). "Kallikrein-related peptidase 6 (KLK6) is a biomarker of gastric cancer associated with poor prognosis." (PMID 27863404, 2016). "Human kallikrein-related peptidase 6 (hK6) is a trypsin-like serine protease encoded by the KLK6, has been reported to be highly expressed in several cancers including gastric cancer." (PMID 23587030, 2013). "We evaluated auranofin (AF), a compound with cytotoxic effects, in KLK6-deficient cells, and we investigated whether KLK6 expression induces autophagy and acquisition of drug resistance in gastric cancer." (PMID 27863404, 2016). "Klk6 is involved in activating proliferation, extracellular matrix remodeling, and tumor invasion, while also promoting the growth and invasion of gastric cancer cells, as well as ovarian and colorectal cancer." (PMID 38203721, 2023). "KLK6 is also expressed in some ascitic fluids from peritoneal metastasis of gastric cancer, but at much lower levels." (PMID 35883559, 2022). "KLK6 was also found in ascitic fluids from patients with peritoneal metastasis from gastric cancers." (PMID 35883559, 2022). "For example, overexpression of KLK6 was found to promote gastric cancer cell growth, migration and invasion in vitro." (PMID 34552064, 2021). "The results of the current study imply that autophagy induction by KLK6 contributes to the tumorigenesis and chemoresistance in gastric cancer." (PMID 27863404, 2016). "We observed increased, stage-dependent autophagy upon KLK6 overexpression in gastric cancer tissues and cells treated with AF." (PMID 27863404, 2016). "KLK6 mRNA levels in lung, pancreas, liver, breast, and colon tissues and KLK6 mRNA and protein levels in various gastric cancer cell lines indicated different patterns of KLK6 expression." (PMID 27863404, 2016). "Modulation of the KLK6 status regulating AF-induced autophagic cell death is a potential therapeutic strategy for gastric cancer." (PMID 27863404, 2016). "To investigate the relationship between drug-induced cell death and KLK6 expression, we performed a cell viability assay upon treatment with various drugs in the gastric cancer cell lines." (PMID 27863404, 2016). "In the xenograft model of gastric cancer, KLK6 expression decreased AF-induced cell death and KLK6-induced autophagy increased AF resistance." (PMID 27863404, 2016). "Immunohistochemistry (IHC) revealed higher KLK6 expression in gastric cancer tissues than in paired normal gastric tissues, and expression was tumor-stage-dependent." (PMID 27863404, 2016). "We also reported a viability screen of gastric cancer cells using various anti-cancer drugs indicating that AF resistance-related cell death depend on the KLK6 expression level." (PMID 27863404, 2016). "Our results suggest that modulation of KLK6 status to regulate AF-induced autophagic cell death is a potential therapeutic strategy for gastric cancer." (PMID 27863404, 2016).
gastric cancer (continued). "The positive rate of KLK6 expression in gastric cancer tissues was 77.5% (100/129), significantly higher than that in adjacent noncancerous tissues (36.5%) and ulcer (33.3%) tissues respectively (P <0.001)." (PMID 23587030, 2013). "KLK6 has previously been shown to be over expressed in gastric cancer and RNAi mediated knockdown of KLK6 in gastric cancer cell lines has been shown to be anti-proliferative and anti-invasive." (PMID 21781349, 2011). "KLK6, or protease M, is highly expressed in several malignancies like ovarian, breast, colon or gastric cancer." (PMID 18854834, 2008). "Similarly, KLK5 also plays a role in the H3N2 influenza virus infection in humans and KLK6 activates autophagy in various gastric cancer cell lines and mediates chemotherapeutic resistance by attenuating auranofin-induced cell death." (PMID 31060300, 2019). "We demonstrate that KLK6 overexpression via induction of autophagy may contribute to acquired chemoresistance in gastric cancer." (PMID 27863404, 2016). "Moreover, KLK6 levels were approximately 5-fold higher in gastric cancer patient sera than in normal sera." (PMID 27863404, 2016). "We previously reported that the serine protease kallikrein-related peptidase 6 (KLK6) is a potential biomarker for colon and gastric cancer because it is highly expressed in these cancers and is important in tumorigenesis." (PMID 27863404, 2016). "Autophagy markers such as LC3B and Atg5, and KLK6 which is gastric cancer biomarker, but not beclin-1, showed increased expression over 16 h after AF treatment." (PMID 27863404, 2016).